MIR636 (microRNA 636)
Synonyms: hsa-mir-636; MIRN636
Gene: MicroRNA gene on chromosome 17 (76,736,450 to 76,736,548, reverse strand). Ensembl gene ENSG00000283805.
Gene Ontology:
Biological process: miRNA-mediated post-transcriptional gene silencing
Cellular component: RISC complex